YAP1 (Yes1 associated transcriptional regulator)
Diseases named in the same sentence as YAP1 in open-access papers (continued):
Sharing a sentence is not in itself a finding about the gene and the disease.
tumor (continued). "In support of that, an inverse relationship between the expression levels of YAP1 and ΔNp63 were reported in lung SCC tumor samples." (PMID 32990596, 2020). "When present, both YAP1/TAZ were diffusely distributed throughout the tumor, with primary expression located in the cytoplasm of tumor cells and nuclear staining in some cases." (PMID 32365528, 2020). "In summary, this project investigated the interactions between ncRNAs and YAP1 and their roles in the regulation of CRC glycolysis and tumour progression." (PMID 33218358, 2020). "Not only that, if YAP1 or SRC of hCAF was knocked down, then its conditioned medium cannot promote tumor cell invasion." (PMID 32066485, 2020). "Using genetic rescues by deleting YAP1 and TAZ from the same cells with LATS1/2 deletion, we demonstrated that either of these paralogs can lead to tumour formation." (PMID 32404936, 2020). "YAP1/TAZ-TEAD also plays an important role in maintaining cancer stem cells (CSCs), the major determinants of tumor recurrence, metastasis and chemoresistance, and modulates the expression of CSC markers." (PMID 33178014, 2020). "In a NF2-mutant sRCC model, YAP1 knockdown and NF2 reconstitution suppressed cell proliferation, tumour growth and invasion, both in vitro and in vivo." (PMID 31959902, 2020). "EMT is a critical process for cancer metastasis and YAP1 is vital to activate the transcriptional programs involved in regulating EMT and tumor growth." (PMID 32154166, 2020). "BT-474.r2T cells were xenografted in a heterotopic mouse model to further examine the role of YAP1 and TEAD1-2 in tumor growth to evaluate in vivo the potential antitumor activity of verteporfin alone or in combination with trastuzumab." (PMID 32365528, 2020). "The results of MTT assays showed that when YAP1 or SRC of hCAF was knocked down, its conditioned medium’s promotion effect on the proliferation capacity of two tumor cells was weakened." (PMID 32066485, 2020). "YAP1 knockdown in JHRCC12 cells suppressed cell proliferation, invasion, and tumour growth and induced change in their morphology." (PMID 31959902, 2020). "Subcutaneous tumor model showed that suppression of CLDN6 expression reduced tumor load, while overexpression of YAP1 reversed this trend of tumor load reduction." (PMID 31827075, 2019). "Our data suggest that genetic targeting of DGUOK induced tumor regression through inhibition of mitochondrial OXPHOS and YAP1 signaling." (PMID 31633874, 2019). "Under mechanical context, YAP1 coordinates with E-cadherin, β-Catenin, and MYC and integrates multiple signaling pathways to contribute to tumor growth." (PMID 30934860, 2019). "To evaluate the antitumor effect in vivo, we tested anti-tumor effects of PVT1- and YAP1-specific ASOs alone or in combination of PVT1 and YAP1 specific ASOs in JHESO xenograft mice model." (PMID 31601234, 2019). "For instance, WDLS, SFT and LMS were almost exclusively positive for nuclear YAP1, whereas higher nuclear TAZ levels were detected in MPNST and AS tumor specimens." (PMID 31873172, 2019). "It has been reported that SIRT1 reacts with the YAP1 protein in HCC cells, thus activating YAPTU/TEAD4 transcription ability and promoting HCC tumor cell growth." (PMID 30961610, 2019). "Only the tumor group showed a significant positive correlation between NMU and YAP1 (GSE15471 r = 0.6082, p < 0.0001; GSE16515 r = 0.3490, p = 0.037; GSE55643 r = 0.4831, p = 0.0009; GSE62165 r = 0.3012 p = 0.0009)." (PMID 31575084, 2019). "RASSF1A is a Hippo pathway scaffold protein that subtracts YAP1 from oncogenic TEAD (TEA domain) transcriptional complexes and promotes tumor-suppressive YAP1/p73 activity." (PMID 31323949, 2019). "This is consistent with the present results showing that YAP1–NMU crosstalk is responsible for collagen accumulation, aggressive tumor types, and metastatic properties in experimental models." (PMID 31575084, 2019).
tumor (continued). "Consistent with the in vitro experiments, in xenograft mouse models, silencing of ERK1 increased tumor volume and weight after injection of MCF7 cells, which was reversed by silencing of YAP1." (PMID 31848326, 2019). "However, some researchers have suggested that YAP1 might function as a tumor suppressor." (PMID 30868052, 2019). "The exogenous full-length YAP1-MAMLD1 fusion localized within the nucleus, similar to human ST-EPN-YAP1 tumor cells." (PMID 31477715, 2019). "Silencing YAP1 can restore hepatocyte differentiation by siRNA-lipid nanoparticles (siRNA-LNPs) in advanced HCC, and leads to tumor regression." (PMID 30961610, 2019). "The positive feedback loop of YAP1 and ECM composition not only maintains tumor growth and metastasis, but also antagonizes chemotherapy." (PMID 30934860, 2019). "By binding with OCT4 through its WW domain, YAP1 promotes SOX2 activity and thus leads to maintenance of tumour stemness." (PMID 28782275, 2018). "Meanwhile, miR-375 targets YAP1, TEAD4, and CTGF and exerts tumor suppressor function involved in Hippo pathway." (PMID 29367737, 2018). "Let-7 exerts its tumor suppressor function in part by inhibiting the expression of numerous oncogenes such as MYC, RAS, YAP1, HMGA2, and CDK6 and by altering cellular bioenergetics, including glucose metabolism." (PMID 30057901, 2018). "YAP1 activation induces aggressive malignant behavior, such as epithelial-to-mesenchymal transition (EMT), proliferation, drug resistance, tumor-promoting microenvironment, and metastases." (PMID 30234141, 2018). "YAP1 is an activator of TEAD1–4 transcription factors and it has been found that TEAD1–4 family members play important role in tumor progression via activating progression-inducing genes (CTGF, Cyr61, and Myc)." (PMID 29850494, 2018). "To determine the role of YAP1 in the development of NSCLC, we first examined YAP1 expression in 14 tumor samples by immunohistochemistry (IHC) assays; we found that YAP1 expression was obviously higher in NSCLC tissues than in paired adjacent tissues." (PMID 29700328, 2018). "IHC analysis confirmed that these tumors express less YAP1 and also show greatly reduced SOX2 and Ki67 protein levels, suggesting that both tumor cell proliferation and the number of progenitor/stem like cells are regulated by YAP1 expression in vivo." (PMID 29383141, 2017). "However, the role of YAP1 and the tumor microenvironment remains unclear." (PMID 28241877, 2017). "To determine if the expression of INSM1 or YAP1 had any clinical significance, we stained a second TMA containing 55 additional SCLC tumor samples for just INSM1 expression because its robust staining and frequent positivity made it easier to score than YAP1." (PMID 29088741, 2017). "A positive correlation was observed between the expression of YAP1 and the expression of proliferation-related genes (KI67 and c-MYC) in tumor specimens." (PMID 28036290, 2017). "YAP1 mRNA and protein levels were higher in PTC tumor tissues than in control tissues, and correlated positively with the levels of proliferation-related genes (KI67 and c-MYC)." (PMID 28036290, 2017). "To assess the role of these signaling proteins during tumor formation and response to SFN, we treated ECS cell tumor xenografts with SFN and monitored the impact on YAP1/∆Np63α level." (PMID 29088716, 2017). "Functional studies have shown that Yap1, in cooperation with the transcription factor Tead2, drives KRASG12D independent tumor maintenance, through a molecular mechanism involving activation of cell cycle and DNA replication program." (PMID 29156578, 2017). "However, the promotion of tumor growth could be abolished by either co-treated cells with miR-16 mimics and YAP1 overexpression lentivirus or co-treated with miR-16 inhibitor and YAP1 shRNA lentivirus, indicating the function induced by miR-16 might be in a YAP1- dependent behavior." (PMID 28915618, 2017).
tumor (continued). "Our results reveal that YAP1 activation exerts a protective role for TNBC cells in radiotherapy and represents a pharmacological target to enhance the anti-tumor effects of DNA damaging modalities in the treatment of TNBC." (PMID 29228705, 2017). "Our studies show that SFN treatment increases YAP1 phosphorylation and degradation, reduces ∆Np63α levels and reduces ECS cell survival, spheroid formation, invasion, migration and tumor formation." (PMID 29088716, 2017). "In MKN1 xenografts, ivermectin suppressed tumor growth, and the sensitivity of MKN1 cells to ivermectin was decreased by YAP1 knockdown." (PMID 29296196, 2017). "Quantitative real-time RT-PCR, Western blot, and immunohistochemistry were performed to measure Nodal and YAP1 mRNA and protein in 20 fresh frozen samples and 220 paraffin-embedded GAC tissues with their paired non-tumor mucosa (PNTM)." (PMID 27325246, 2016). "Increased YAP1 and GP130 expression, STAT3 and ERK phosphorylation were also observed in Δhep tumour-bearing livers." (PMID 28000790, 2016). "In this study, we measured mRNA and protein expression of both Nodal and YAP1 in GAC and paired non-tumor mucosa (PNTM)." (PMID 27325246, 2016). "As a result, we found at least one tumor initiating event (tumor growth) in 811 TICs transfected with empty vectors (TIC frequency of 1/811) and 173 TICs with active Yap1 (TIC frequency of 1/173)." (PMID 26695440, 2016). "BALB/c-nude mice were injected subcutaneously into the right flanks with BGC-823, YAP1-shRNA BGC-823, MKN45, GES-1, and GES-1-YAP1 cells, and let to grow for 4 weeks to establish the heterotopic xenograft tumor mice model." (PMID 27835600, 2016). "Stable YAP1 silencing inhibited the proliferation, migration, and invasion of BGC-823 GC cells in vitro and inhibited the growth of xenograft tumor and hematogenous metastasis of BGC-823 GC cells in vivo." (PMID 27835600, 2016). "Because basic expression of active Yap1 is present in TICs, our lentivirus vector further enhanced active Yap1 and dramatically promoted TIC self-renewal and tumor initiation in serial passages." (PMID 26695440, 2016). "Yap suppression in allograft tumors generated from KP cells results in decreased cell proliferation and tumor growth, and treatment with verteporfin to block the YAP–TEAD interaction decreased transcription of Yap1 target genes." (PMID 26389076, 2015). "YAP1 overexpression in the intestine correlates with downregulation of the tumor suppressor PTEN, exerting its tumor-suppressive functions in part by decreasing Cyclin D1 levels." (PMID 25601544, 2015). "As YAP1 is a direct target of miR-15a and miR-16-1 in GAC, we then checked if siRNA-mediated knockdown phenocopied the tumor-suppressive function of miR-15a and miR-16-1." (PMID 25743273, 2015). "c-MYC, SRC and YAP1 were expressed in most samples (WT and control rhabdoid tumours) with c-MYC elevated in NCAM+ALDH1+ tumour." (PMID 23239665, 2013). "Recently, Roepman and coworkers reported that cluster B genes IL6, IL8, YAP1, and BIRC2 are upregulated in metastatic HNSCC tumor specimens." (PMID 17498291, 2007). "Importantly, two clinical drugs, the RhoA inhibitor simvastatin and the YAP1/TEAD inhibitor verteporfin were determined to be the disruptors of this feed-forward signaling axis, inhibiting ICC tumor growth." (PMID 41513610, 2026). "Notably, this pathway can be reversed by activating YAP1 through MST1/2 inhibition, which shifts macrophages from an M2 to an M1 phenotype, enhancing CD8+ T-cell activity and mitigating tumor progression." (PMID 40330466, 2025). "YAP1-driven EMT programs and integrin signaling may enhance tumor cell plasticity and promote clearance of micrometastases, particularly from lymphatic compartments." (PMID 40731926, 2025).
tumor (continued). "YAP1/TAZ then connects with the transcription factor TEAD (transcriptional enhancer activator domain) in the nucleus, which initiates the expression of DNA repair genes, further promoting tumor cell survival and enhancing resistance to radiation." (PMID 40699764, 2025). "Collectively, these findings suggest that PP1γ may play an important role in tumor invasiveness and metastasis of ESCC through the PP1γ/YAP1/SOX2 axis." (PMID 40626009, 2025). "However, in the tumor stroma, only CD4-positive cell density showed a significant correlation with YAP1-positive cell density (r = 0.690, P = 0.008)." (PMID 40051494, 2025). "Given that both CDK4/6 and DUB3 contribute to tumor progression in HCC by stabilizing YAP1, we hypothesized that DUB3 might serve as a linker between CDK4/6 and YAP1." (PMID 40307228, 2025). "YAP1 expression emerges while ASCL1 and NEUROD1 expression decreases, resulting in a mixed tumour with some YAP1 and ASCL1 expressed side-by-side within the same tumour." (PMID 41290592, 2025). "As ECM stiffness generally regulates tumor progression through its receptors, we systematically screened several common ECM-sensing receptors (ITGB1, CD44, Piezo1, Piezo2, YAP1, Syndecan1, and DDR1) via siRNA knockdown, and confirmed the knockdown efficiency by conducting qRT-PCR analyses." (PMID 40685383, 2025). "NaB increased YAP1 phosphorylation and decreased the transcription of CTGF and CYR-61 in HCT-116 cells, along with upregulation of SAV1 and downregulation of TAZ, suggesting partial reactivation of Hippo tumor suppressor functions." (PMID 40872562, 2025). "After tumorigenesis, due to reduced fluid flow, circulating tumor cells (CTCs) have increased lymphatic system retention, which may activate YES-related protein 1 (YAP1) and transcriptional coactivators with PDZ-binding motif (TAZ) signaling pathways in CTCs." (PMID 40216744, 2025). "Additionally, YAP1 expression is more frequently detected in recurrent or treatment-resistant SCLC tumors, therefore supporting its critical role in tumor progression and plasticity." (PMID 40333678, 2025). "Additionally, it has been reported that a positive regulation of CCBE1 by YAP1/TAZ/BRD4 and their pro-tumor lymphangiogenesis in colorectal cancer." (PMID 41184230, 2025). "Furthermore, YAP1 target genes such as CTGF and CYR61 contribute to extracellular matrix remodeling and angiogenesis, thereby facilitating tumor progression." (PMID 40872562, 2025). "Interestingly, YAP1-induced upregulation of LATS2 in HCvECs is a critical driver of this senescence process, which acts as a potent tumor-suppressive mechanism in normal cervical epithelial cells." (PMID 41256331, 2025). "Overall, YAP1-positive cells were predominantly located in the tumor stroma rather than infiltrating the tumor parenchyma." (PMID 40051494, 2025). "Phosphorylation status also affects transcriptional regulation, such as PLK1-mediated Ser326 phosphorylation of OTUD3, which stabilizes YY1 and supports tumor growth, or the downregulation of PCYT2, which reduces YAP1 phosphorylation, enhancing metastasis through SNAIL2 and ZEB1 activation." (PMID 41359051, 2025). "Additionally, EFHD1 overexpression reduced nuclear YAP1, nuclear TAZ, and TEAD1 levels, thereby preventing YAP1/TAZ nuclear translocation and interaction with TEAD1, a key process in tumor progression." (PMID 39895792, 2025). "Collectively, our study uncovers a novel oncogenic role of the CDK4/6‐DUB3 pathway, which promotes YAP1 stabilization and tumor‐promoting function, highlighting that targeting CDK4/6 offers a potential therapeutic strategy for CRC with aberrantly upregulated DUB3 and YAP1." (PMID 39968498, 2025). "Through the regulation of YAP1, TEAD4 binds to the TIAM1 enhancer region, thereby activates the expression of TIAM1 and subsequently increases the activity of RAC1 and induces the formation of invadopodia formation and promotes tumor metastasis." (PMID 40746611, 2025).
tumor (continued). "In addition, using a murine model of subcutaneous transplantation of HCC cells, it was found that the combined use of the YAP1 inhibitor, verteporfin, and DDP led to significant tumor regression." (PMID 40918140, 2025). "In murine xenograft models, YAP1 depletion in FaDu cells slows tumor growth by ∼50% and reduces pulmonary metastases, and treatment with Verteporfin (a YAP–TEAD inhibitor) further suppresses tumor progression and diminishes resistant lesions." (PMID 40486910, 2025). "On the contrary, restoration of YAP1 expression by pharmaceutical inhibition of MST1/2 induced conversion of M2-to-M1-like polarized MФs, elevating the infiltration of CD8+ T cells and attenuating tumor growth." (PMID 39198883, 2024). "Additionally, vestigial-like protein-4 (VGLL4) has been shown to suppress YAP1/TEAD-dependent signaling in epidermal squamous cell carcinoma, reducing tumor formation and EMT by inhibiting YAP1-dependent transcription and target gene expression." (PMID 39595118, 2024). "Notably, Akt-YAP1 in Sox9 LKO led to significantly decreased survival and a much greater and more lethal tumor burden, as seen by significantly greater LW/BW and macroscopically, as compared to the Akt-YAP1 in LWT mice." (PMID 39273023, 2024). "Importantly, decursin induced apoptosis of tumor cells can be reversed by selective MST1/2 inhibitors, which confirms that the antitumor effect of decursin in liver tumor depends on Hippo/YAP1 pathway." (PMID 38550587, 2024). "In summary, by interfering with the AR/FlnA complex, targeting several extracts, and inhibiting the activity of key factors, such as YAP1, CXCL12, and TGF-β, the pro-tumor function and ability to maintain the CAF tumor can be effectively impaired, providing a new approach for PCa treatment." (PMID 39092186, 2024). "Akt and YAP1 plasmids were co-delivered by SB-HDTVI into Alb-Cre;Sox9flox/flox (Sox9 LKO) or Sox9flox/flox (LWT) in which Sox9 was deleted HC and BEC initiated at around day E15, resulting in chronic developmental deletion prior to tumor formation." (PMID 39273023, 2024). "Additionally, coincident DAB2 and active-YAP1 upregulation was observed in GC tumor tissues and indicated a poor prognosis, indicating that elevated DAB2 and active-YAP1 expression levels served as predictive biomarkers for GC." (PMID 38481347, 2024). "Interestingly, NF2, a key tumor suppressor, responsible for activation of LATS1 (Large tumor suppressor homolog 1) and increased YAP1 phosphorylation, was significantly up‐regulated after silencing of TRIM65 expression." (PMID 39005234, 2024). "Here, we reviewed overexpressed YAP1 stimulates the production of cytokines, leading to increased infiltration of macrophages, MDSCs, and Tregs, ultimately resulting in an immunosuppressive TME that promotes tumor initiation and progression." (PMID 38550587, 2024). "We further explored the role of YAP1 in CRPC and showed that YAP1 may be a more suitable target than GPX4 to increase ferroptosis, inhibit tumor recurrence and metastasis, and improve drug sensitivity." (PMID 37773303, 2024). "Upregulation of YAP1 and MALAT1 is correlated with poor prognosis in CRC patients, and the silencing of these genes could inhibit tumor growth, EMT, and angiogenesis in vivo and in vitro." (PMID 39431199, 2024). "In short, YAP1 was identified as a critical regulator of CAF activation; elevated levels of YAP1 are considered to activate CAFs, resulting in the stiffening of the ECM and the progression of the tumor." (PMID 38550587, 2024). "In addition, YAP1 mediates the metabolic transformation of fatty acid oxidation (FAO) in tumor cells, which promotes tumor lymph node metastasis." (PMID 38550587, 2024). "We therefore derived Gp130FF tumor organoids and used CRISPR/Cas9-mediated gene editing to impair Yap1 expression by co-transfecting organoids with the tracrRNA containing an ATTO550 label and the guide crRNA that targets exon 1 of the mouse Yap1 gene." (PMID 37957015, 2024).